LUM (lumican)
Diseases named in the same sentence as LUM in open-access papers (continued):
Sharing a sentence is not in itself a finding about the gene and the disease.
fibrosis (4 papers, 2012 to 2025). the formation of excess fibrous connective tissue in an organ or tissue in a reparative or reactive process. "In our fibrosis cellular model, firstly, we observed ER fragmentation and smaller LD size in adipocytes in 3D cultures that were exposed to lumican." (PMID 38139006, 2023). "By contrast, VCAN_eCAF, substantially expanded in fibrotic regions (Fibrosis+ LM) and highly expressing core ECM genes (LUM, VCAN and collagens), may constitute an activated, terminal state that dominates the pathological ECM remodeling." (PMID 41258075, 2025). "Though LUM is considered to be essential for hepatic fibrosis, its function in hepatocarcinogenesis has not yet been determined." (PMID 35659630, 2022).
osteoarthritis (4 papers, 2019 to 2025). A noninflammatory degenerative joint disease occurring chiefly in older persons, characterized by degeneration of the articular cartilage, hypertrophy of bone at the margins and changes in the synovial membrane. "In osteoarthritis, overexpressed LUM has a proven association with the cartilage degradation and macrophage polarization." (PMID 34516336, 2021). "Opticin null mice showed protection against osteoarthritis and it was found that these mice had increased levels of lumican and epiphycan, and decreased levels of fibromodulin." (PMID 32764753, 2020). "Additionally, LUM has been shown to be increased in various inflammatory-like conditions and to be able to regulate multiple inflammation-related pathways in different diseases, such as osteoarthritis, keratitis, pancreatitis, and heart failure." (PMID 34516336, 2021).
pancreatic ductal adenocarcinoma (4 papers, 2019 to 2022). An infiltrating adenocarcinoma that arises from the epithelial cells of the pancreas. "The presence of stromal lumican in the ECM surrounding pancreatic ductal adenocarcinoma (PDAC) inhibits cancer cell replication and is associated with improved patient outcomes after multimodal therapies." (PMID 31406961, 2019). "Thus, lumican was shown to inhibit cancer cell proliferation inthe early stages of pancreatic ductal adenocarcinoma (PDAC)." (PMID 34572532, 2021). "In pancreatic ductal adenocarcinoma (PDAC) following surgical resection, high levels of lumican are correlated with decreased recurrence and prolonged patient survival, implicating lumican as an anti-oncogenic agent in this tissue-specific context." (PMID 34982945, 2022). "A study with patient tumor tissues, ex-vivo cultures of patient-derived xenografts (PDX), pancreatic ductal adenocarcinoma (PDAC) stellate, and tumor cells was conducted to investigate whether hypoxia within the tumor microenvironment alters stromal lumican expression and secretion." (PMID 34572532, 2021).
squamous cell carcinoma (4 papers, 2015 to 2024). A carcinoma arising from squamous epithelial cells. "Matsuda Y and colleagues studied lumican expression in a series of adenocarcinomas and squamous cells carcinomas of the lung by using IHC." (PMID 25961303, 2015).
cervical cancer (3 papers, 2016 to 2023). A primary or metastatic malignant neoplasm involving the cervix. "The proteins that showed an increased expression in cervical cancer in comparison with normal cervix cells were: Mimecan, Actin from aortic smooth muscle and Lumican." (PMID 27601940, 2016). "Western blot analysis confirmed that LYZ, ORM1, LYN, STMN1 significantly increased in cervical cancer, while LUM, BGN, KRT4 significantly decreased." (PMID 27690342, 2016). "The present study revealed that the N-glycopeptide of MASP1, LUM, ATRN, CO8A, CO8B and CO6 may be potential biomarkers for predicting the efficacy of chemotherapy for cervical cancer." (PMID 37519786, 2023). "On the other hand, LUM, BGN and KRT4 significantly decreased in cervical cancer samples." (PMID 27690342, 2016).
Corneal opacity (3 papers, 2017 to 2025). A reduction of corneal clarity. "The crucial role of LUM in visual functions is further demonstrated by growing evidence implicating LUM in various ocular defects such as corneal opacity and high myopia." (PMID 28396824, 2017).
coronary atherosclerosis (3 papers, 2021 to 2026). Atherosclerosis of the coronary vasculature. "Previous reports indicated that LUM was expressed in smooth muscle cells in human coronary atherosclerosis and promoted the formation of collagen fibers." (PMID 37089432, 2023). "A study reported LUM expression in the outer layer of SMCs and atheromatous plaques in patients with coronary atherosclerosis." (PMID 34310653, 2021).
COVID-19 (3 papers, 2021 to 2023). A disease caused by infection with severe acute respiratory syndrome coronavirus 2. "We found that lumican levels were depleted in the COVID-19 groups compared to the non-COVID-19 and healthy groups and is also associated with some glycerophospholipids in block-wise association testing." (PMID 35842456, 2022).
diabetes (3 papers, 2020 to 2024). "In animal and model studies of diabetes mellitus (DM), treatment with human recombinant lumican has been shown to enhance lipolysis in adipocytes and elevate free fatty acid levels in the body." (PMID 38774257, 2024). "Urinary excretion of CD14, HEXA, and LUM was significantly elevated in early diabetes as reported by Singh and colleagues, but was variable in the study by Suh and colleagues." (PMID 32453760, 2020). "In addition, urinary excretion of lumican, a core protein of keratan sulfate proteoglycan, was higher in diabetes with a fold change of 2.16 (Q = 0.0445)." (PMID 32453760, 2020).
Hyperglycemia (3 papers, 2018 to 2019). An increased concentration of glucose in the blood. "Results demonstrated successful differentiation of hCSSCs into keratocytes with KERA and LUM genes being highly expressed and only modest effects of hyperglycemia on collagen or proteoglycan expression." (PMID 30470798, 2018). "Then, we performed Western blot analysis to validate our spectral counting results, and determine whether hyperglycemia led to increased lumican expression in the cornea of rats." (PMID 30453691, 2018).
liver cancer (3 papers, 2017 to 2022). An epithelial or non-epithelial malignant neoplasm that arises from the liver. "In the present study, we found that the expression levels of two proteoglycans, decorin and lumican, were both significantly positively associated with β-defensin 1 expression, and reduced in liver cancer." (PMID 29042578, 2017). "In liver cancer, silencing Lumican resulted in decreased cancer cell migration by inhibiting ERK1/JMK signaling." (PMID 36361971, 2022). "Transfection of hepatic cancer cells with shRNAs specific for lumican resulted in decreased invasion and migration mediated by reducing the ERK-1 and JNK activation status." (PMID 34572532, 2021). "On the other hand, the two proteoglycan genes, DCN and LUM, were both downregulated in liver cancer." (PMID 29042578, 2017). "In liver cancer cells, silencing lumican by shRNA reduced cell invasion and migration via inhibiting the activation of the ERK1/JNK pathway, suggesting that lumican is a positive regulator of these cells’ migratory abilities." (PMID 34572532, 2021). "In addition, hepatic cancer HepG2 and MHCC97H cells express more lumican in comparison with normal Lo02 hepatocytes." (PMID 34572532, 2021). "Similar LUM expression level was lower in liver cancer specimens compared to non-tumor specimens in GSE25097 (P < 0.001), GSE14520 (P < 0.001) and GSE36376 (P = 0.025)." (PMID 29042578, 2017).
lymph node metastasis (3 papers, 2020 to 2021). "Notably, lumican expression was positively associated with the spread of lymph node metastasis and had lower survival rates." (PMID 34572532, 2021). "Specifically, lumican was detected in the cytoplasm of cancer cells in 62.7% of 158 patients undergoing curative surgery for advanced colorectal cancer with lymph node metastasis." (PMID 34572532, 2021).
nonalcoholic fatty liver disease (3 papers, 2019 to 2024). "In addition, LUM has been identified as a biomarker for advanced fibrosis in non-alcoholic fatty liver disease." (PMID 37090703, 2023).
posterior amorphous corneal dystrophy (3 papers, 2011 to 2024). Posterior amorphous corneal dystrophy (PACD) is a very rare form of stromal corneal dystrophy characterized by irregular amorphous sheet-like opacities in the posterior corneal stroma and in Descemet membrane and mildly impaired vision. "DCN is also lost together with keratocan (KERA), lumican (LUM), and epiphycan (EPYC) in posterior amorphous stromal dystrophy (PACD), which is characterized by stromal opacities in the first decade of life." (PMID 39394466, 2024). "A human genome-wide linkage analysis of posterior amorphous corneal dystrophy identified a region of human chromosome 12 that is orthologous to a Mcs6 region that contains genes DCN, LUM, KERA, and EPYC." (PMID 21625632, 2011).
prostate tumor (3 papers, 2013 to 2025). "Although real-time PCR and immunostaining of LUM showed its upregulation in the reactive stroma surrounding prostate tumors, in vitro and in vivo studies showed that LUM suppresses migration and the invasion of metastatic PC cells." (PMID 41470114, 2025). "In prostate tumor tissues, a marked attenuation of total decorin and lumican expression was evident, whereas syndecan-1 and glypican-1 expression was increased in tumor stroma and attenuated in tumor epithelial cells." (PMID 32847060, 2020). "On the other hand, the expression of lumican in the stroma circumjacent to primary prostate tumors was found to attenuate the progression of this malignancy." (PMID 32847060, 2020). "In prostate tumours, complex changes in proteoglycans occur, with a common trend towards decrease of decorin and lumican expressions, and increase an overall expression of syndecan-1 and glypican-1, shifted from the epithelial cells to tumour stroma." (PMID 23691363, 2013). "In this study, expression of cell surface and stromal proteoglycans (glypican-1, perlecan, syndecan-1, aggrecan, versican, NG2, brevican, decorin, and lumican) in normal tissue and prostate tumours was determined by RT-PCR analysis and immunostaining with core protein- and GAG-specific antibodies." (PMID 23691363, 2013). "As a result, expression patterns for main proteoglycans in prostate tumours were highly individual with an ubiquitous expression for versican and tendency for the decreased decorin and lumican expressions and increased syndecan-1 and glypican-1 expressions in tumour tissues." (PMID 23691363, 2013). "Whereas the versican expression level was relatively similar both in normal and malignant prostate tissues (35–40% of increase for versican expression was not considered as significant), decorin and lumican expressions trend towards to be decreased in prostate tumours up to 2-fold." (PMID 23691363, 2013). "Earlier, the only published paper showed lumican upregulation in BPH when compared with normal prostate tissues, with no data for lumican expression in prostate tumours." (PMID 23691363, 2013).
Sepsis (3 papers, 2015 to 2026). Sepsis is defined as life-threatening organ dysfunction caused by a dysregulated host response to infection. "The present study of the ECM protein identified lumican as a novel modulator of the host response to inflammation and sepsis." (PMID 26081832, 2015). "It was demonstrated that lumican exacerbated LPS-induced inflammation and renal injury in murine models of sepsis." (PMID 26081832, 2015). "It has been reported that the circulating level of lumican was increased in human and mouse during sepsis and mice lacking lumican showed poor bacterial clearance." (PMID 39292008, 2024).
aortic valve calcification disease (2 papers, 2024 to 2025). "Previous studies have found that THBS2, COL1A1, and LUM are closely related to aortic valve calcification disease." (PMID 39749331, 2024).
chondrosarcoma (2 papers, 2024). A malignant cartilaginous matrix-producing mesenchymal neoplasm arising from the bone and soft tissue. "In chondrosarcoma cells, LUM and IGF-IR interact and consequently activate the AKT signaling pathway, which positively regulates cell proliferation and inhibits apoptosis." (PMID 39685635, 2024).
chronic pancreatitis (2 papers, 2011 to 2021). A chronic inflammatory process causing damage and fibrosis of the pancreatic parenchyma. "The up-regulation of lumican is detected in the acinar cells of chronic pancreatitis (both MCP and SCP) and PDAC." (PMID 22132114, 2011). "The IHC analysis of lumican, versican and Col14A1 confirmed their up-regulation in chronic pancreatitis and pancreatic adenocarcinoma, and provided additional insights on how they behave at cellular level in association with the diseases." (PMID 22132114, 2011).
Cirrhosis (2 papers, 2011 to 2016). A chronic disorder of the liver in which liver tissue becomes scarred and is partially replaced by regenerative nodules and fibrotic tissue resulting in loss of liver function. "Taken together, it implies that PPIs among COL1A1, COL1A2, VWF and LUM may participate in the induction of cirrhosis and play roles in the progression from cirrhosis to HCC." (PMID 21526182, 2011). "Proteoglycan expression revealed the up-regulation of LUM and PRG2, while the abundance levels of BGN, that showed a gradual decrease during fibrosis progression, were found underexpressed up to 12 times in cirrhosis." (PMID 26998606, 2016).
colorectal adenocarcinoma (2 papers, 2021 to 2023). The most common type of colorectal carcinoma. "In the present study, we confirmed high LUM mRNA expression in colorectal adenocarcinoma (COAD) through the UALCAN database." (PMID 33493133, 2021).
cornea diseases (2 papers, 2019 to 2024). "This suggests that the loss of lumican and keratocan under high curvature has potential links to cornea diseases associated with shape deformation, leading to cloudiness and a disorganized structural arrangement." (PMID 38464213, 2024). "Lumican knockout (Lum-/-) mouse model can mimic congenital corneal diseases, involving stromal opacities, secondary to the distorted arrangement of collagen fibrils." (PMID 31212734, 2019).
glaucoma (2 papers, 2022 to 2025). Increased pressure in the eyeball due to obstruction of the outflow of aqueous humor. "Another recent study showed that lumican was negatively associated with mean defect (MD) values of a visual field test in patients with glaucoma, influencing the aqueous outflow resistance by trabecular meshwork reformation." (PMID 35571611, 2022).
glioma (2 papers, 2023 to 2024). A benign or malignant brain and spinal cord tumor that arises from glial cells (astrocytes, oligodendrocytes, ependymal cells). "Next, we interrogated the glioma cohorts from TCGA and CGGA databases to further examine the expression and correlation characteristics of RUNX1, FOSL2, FN1, COL4A1, and LUM in GBM tumorigenesis." (PMID 38286983, 2024).
glomerulosclerosis (2 papers, 2021 to 2024). A hardening of the kidney glomerulus caused by scarring of the blood vessels. "It has been reported that the LUM protein and its family member decorin accumulate strongly in the advanced glomerulosclerosis stage of DN." (PMID 34249963, 2021). "As a component of the ECM, lumican plays a role in collagen fiber formation, interacts with transforming growth factor-β1 (TGF-β1), and contributes to renal cell death in DN by promoting glomerulosclerosis and renal tubular fibrosis, aligning with our enrichment analysis findings." (PMID 38774257, 2024).
head and neck squamous cell carcinoma (2 papers, 2014 to 2017). A squamous cell carcinoma that arises from any of the following anatomic sites: lip and oral cavity, nasal cavity, paranasal sinuses, pharynx, larynx, and salivary glands. "LUM was also identified as a cisplatin- (CIS) resistant related gene in head and neck squamous cell carcinoma (HNSCC)." (PMID 29088800, 2017). "LUM overexpression has been reported in Cis-resistant head and neck squamous cell carcinoma cell lines and in patients not responding to treatment with Cis-based combination chemotherapy." (PMID 24804215, 2014).
Hypertension (2 papers, 2021 to 2023). The presence of chronic increased pressure in the systemic arterial system. "The reduced regulation of COL1 and Lumican in the aorta of the trained SHR could contribute to decreased vessel rigidity observed in hypertension." (PMID 37239052, 2023).
keloid (2 papers, 2022 to 2024). An irregularly shaped, elevated mark on the skin caused by deposits of excessive amounts of collagen during wound healing. "Elevated expression of LUM in keloids contributes to abnormal collagen deposition; however, LUM can also alleviate hypertrophic scarring by suppressing integrin-focal adhesion kinase (FAK) signalling." (PMID 38474072, 2024). "The finding that Lumican, a collagen fibril assembly regulator, and collagen V levels appear to be highly overexpressed in keloid tissues support the hypothesis that increased collagen levels contribute to keloid and hypertrophic scarring." (PMID 35371887, 2022).
keratitis (2 papers, 2013). A corneal disease that is characterized by inflammation of the cornea. "CXCL1 was shown to be temporally up regulated in an LPS treated sterile keratitis model in the mouse, but its increase in lumican-deficient corneas was lower than that of wild types." (PMID 23358433, 2013). "Similarly, CXCL1 levels in the sterile LPS-keratitis model was reportedly increased in the anterior chamber of mice deficient in lumican and keratocan, another corneal proteoglycan." (PMID 23358433, 2013). "Given PMN recruitment is crucial to the inflammatory response in keratitis, lumican could play an active role in pathogenesis of infectious and noninfectious keratitis." (PMID 24558602, 2013).
lymphoma (2 papers, 2020 to 2022). A malignant (clonal) proliferation of B- lymphocytes or T- lymphocytes which involves the lymph nodes, bone marrow and/or extranodal sites. "Given the sizes of the ß-coefficients of the extracellular matrix proteins lumican and periostin in the 8-protein regression equation, intra-lymphoma variability in extracellular matrix may significantly affect the GCB score." (PMID 32398793, 2020). "The first gene we observed using this approach was Lumican (LUM), which is a member of the small leucine-rich proteoglycan family (SLRPs), and was substantially upregulated in lymphoma (log2 fold change = 11.1, FDR p-value = 1.11 × 10−145)." (PMID 36873459, 2022).
Marfan syndrome (2 papers, 2020 to 2021). A disorder of the connective tissue. "Another study using a mouse model to examine transcriptomic changes during aortic aneurysm development in Marfan syndrome identified differential expression patterns of LUM in SMC." (PMID 34310653, 2021). "Marfan Syndrome-associated MVP is accompanied by myxomatous changes in the ECM as indicated by an abnormal accumulation of proteoglycans, largely decorin, versican and lumican and changes in collagen fibers including increased expression." (PMID 32824919, 2020).
medulloblastoma (2 papers, 2023 to 2024). A malignant, invasive embryonal neoplasm arising from the cerebellum. "A recent study in medulloblastoma has described that Lumican can be specifically located on the periphery of nodules of the low-risk subset of medulloblastoma, but it is absent on the nodules of the most aggressive subtype and frequently associated with metastases." (PMID 39796053, 2024). "In contrast, in medulloblastoma in children, extracellular Lumican is detected in the low-risk group but not in aggressive tumors." (PMID 39796053, 2024).
pancreatic adenocarcinoma (2 papers, 2011 to 2021). "Other studies of lumican in pancreatic adenocarcinoma suggests an increased risk for invasion and poor prognosis for patients who have strong staining in the cancer-associated stromal cells." (PMID 22132114, 2011).